EGFR (epidermal growth factor receptor)
Diseases named in the same sentence as EGFR in open-access papers (continued):
Sharing a sentence is not in itself a finding about the gene and the disease.
tumor (continued). "Meanwhile, the EGFR system is believed to be involved in tumour metastases as well as angiogenesis, which are two important phenomena that promote tumour progression." (PMID 35681586, 2022). "We used a two-dimensional (2D) well plate and a 3D lung chip to evaluate the effects of different EGFR-targeting drugs (gefitinib, afatinib, and osimertinib) on tumor cells." (PMID 36005014, 2022). "The dysregulation of EGFR can lead to uncontrolled cell proliferation, angigenesis, and migration, which contribute to tumour growth and spread, and therefore presents as an important therapeutic target." (PMID 36290844, 2022). "mCardinal FP-DL-HBcs with affibodies (mC-DL-HBcs [aff+]) were successfully internalized into EGFR-overexpressing tumor cells and retained a higher fluorescence intensity than mCardinal FP." (PMID 36714624, 2022). "In a small study using an EGFR exon 19-deleted patient derived xenograft model (CTG-2531) we observed delayed tumor regrowth using a combination with 0.5 mg/kg AZD5153." (PMID 36575215, 2022). "When a tumor grows, tumor cells need to proliferate and differentiate rapidly, EGFR-related signaling pathways are activated in the cells." (PMID 35105871, 2022). "EGFR mutation is usually connected with low PD-L1 expression, while KRAS and MET alterations are associated with higher PD-L1 tumour expression." (PMID 35329956, 2022). "It has been observed that EGFR-mutant tumour cells can enter a drug-tolerant state reminiscent of cellular senescence that enables ongoing survival predominantly through resistance to or inhibition of apoptosis." (PMID 36212398, 2022). "We thus adopted the Johnson-Verhaak nomenclature to label EGFR+ tumor clusters with cluster 22 proliferating stem-like cells displaying the most proliferating cells." (PMID 35624211, 2022). "To identify ceRNA networks of significant prognostic value in LUAD, we further explored RNA expression levels in high and low EGFR expression groups as well as in tumor and adjacent normal lung tissue." (PMID 36291859, 2022). "Overall, these results demonstrate that hinge truncation increases tumor selectivity for EGFR sdCAR-T cells even in simultaneous co-culture with both healthy cells and cancer cells." (PMID 35935988, 2022). "The tumours were excised after 26 days of tumour inoculation, and it was found that the average tumour weight of the group treated with EGFR/PEG-SSNs complexes had the most negligible tumour weight compared to the control and empty NPs groups." (PMID 36412852, 2022). "In tumor cells with high EGFR expression, tumor cells produce vascular endothelial growth factor (VEGF) and interleukin-8, which regulate and promote intratumoral vascular invasion." (PMID 36085020, 2022). "Panitumumab is an EGFR antagonist which binds specifically to EGFR on tumor cells and then competitively inhibits the binding of ligands for EGFR." (PMID 35664074, 2022). "EGFR was a transmembrane receptor and was related to the proliferation, angiogenesis, and apoptosis of tumor cells." (PMID 36561345, 2022). "Listed are all clinical trials with senolytics and senomorphics combined with anti-EGFR therapies applied to different tumor types." (PMID 36712972, 2022). "It has been reported that glycosylation-modified MUC1 promotes tumor growth by regulating the epidermal growth factor receptor (EGFR) pathway in EC cells." (PMID 35752750, 2022). "In the tumor microenvironment, the EGFR system activates paracrine and autocrine circuits that promote tumor growth and progression." (PMID 35406622, 2022). "Preclinical data have shown that combining a KrasG12C inhibitor with an EGFR antibody or an SHP2 inhibitor – two proteins active upstream of RAS – diminished tumor growth in KrasG12C‐mutant cancers." (PMID 35398967, 2022). "Concomitantly, Cetuximab (CTX, an anti-EGFR monoclonal antibody) was also designed to bind to LPs, which also results in the promotion of tumor cell selectivity and therapeutic activity." (PMID 36568152, 2022).
tumor (continued). "Predominant alterations in NSCLC occur in epidermal growth factor receptor (EGFR), mainly located in exon 18 to 21, resulting in tumor cell proliferation, differentiation and migration." (PMID 36188595, 2022). "Among the 94 patients studied, CK 5/6 staining was seen in the cytoplasm of the tumour cells in 31 patients (33%), EGFR in 47 patients (50%), E-Cadherin in 32 patients (34%) and Androgen receptor in 32 patients (34%)." (PMID 35463732, 2022). "Today, the clinical treatment decisions in EGFR-mutant LUAD are primarily based on tumor genetic profiles." (PMID 35203491, 2022). "A benefit to the use of HDAC inhibitors in combination with EGFR inhibitors (to increase EGFR inhibitor efficacy or decrease tumor resistance) has been observed in clinical trials." (PMID 35188360, 2022). "There were 48 intersected targets such as EGFR, AKT1, and TNF that were associated with patients’ outcomes by the univariate Cox analysis, and most of them had increased expression in the tumor as compared to normal tissues." (PMID 35873484, 2022). "Decorin can also inhibit tumor growth by blocking epidermal growth factor receptor (EGFR) and ErbB4 dimerization." (PMID 36033387, 2022). "In this experiment 5/5 mice treated with EGFR-sdCAR cells showed complete tumor regression and significantly enhanced survival relative to those receiving untransduced T cells." (PMID 35935988, 2022). "cfDNA testing is now a recognised method for testing for EGFR variants in NSCLC to influence targeted therapy treatment decisions, with its use complementing that of testing of tumour tissue." (PMID 35820813, 2022). "In cancers, the upregulation of HER4, a member of the epidermal growth factor receptor (EGFR) family, increases metabolic processes associated with tumor promotion, including glycolysis, OXPHOS, and glutaminolysis." (PMID 36139766, 2022). "As there are a number of molecules that have been developed to bind and inhibit EGFR, along with applicability to multiple different tumor types, EGFR should be an appealing target for FGS." (PMID 35053365, 2022). "Macrophages can promote proliferation of tumor by secreting growth factors including epidermal growth factor receptor (EGFR)." (PMID 36569220, 2022). "Recombinant anti-EGFR CAR-T cells exhibits cytolytic activity specifically against tumor cells that are EGFR-positive." (PMID 36423060, 2022). "Attenuated signaling in hinge-truncated EGFR-sdCAR constructs increased selectivity for antigen-dense EGFR-overexpressing cells over an EGFR-low tumor cell line or healthy donor derived EGFR-positive fibroblasts." (PMID 35935988, 2022). "Ligand binding to EGFR is also known to induce tumor progression through activation of downstream pathways, including PI3K/AKT." (PMID 36361620, 2022). "In a mouse study, anti-PD1 treatment of EGFR-mutant lung tumors has shown that these 2 pathways interact with each other by stopping tumor growth and increasing survival." (PMID 35642342, 2022). "Through antibody-dependent cell-mediated cytotoxicity (ADCC), cetuximab directs cytotoxic immune effector cells toward EGFR-expressing tumor cells, potentially contributing to its antitumoral impact." (PMID 35455247, 2022). "Due to its conserved signaling gatekeeper function as a major network bottleneck, SIAHON/OFF expression is well-positioned to serve as a direct readout of tumor-driving EGFR/K-RAS/MEK/MAPK pathway activation (ON)/inactivation (OFF) in TNBC." (PMID 36176751, 2022). "Only one previous study proposed two predictive models for groin node metastases based on four parameters (depth of infiltration, grade of differentiation, tumor diameter, and EGFR), but only the first two were independent predictors." (PMID 35463308, 2022). "In contrast, positive control (H1650 extracted DNA) and the tissue microdissection of the pre-treatment tumor showed a short peak (86 or 89 bp) indicating EGFR ex19del positivity with the peak (103 bp) indicating the presence of wild type." (PMID 36505794, 2022).
tumor (continued). "Xi used the phage display technology and obtained the VHH domains called AS33595 and AS32611 specific to the essential and effective tumor target epidermal growth factor receptor (EGFR)." (PMID 36479130, 2022). "The surface-modified AuNPs were then combined with the tumor cell marker EGFR to achieve targeted localization to A549 cells." (PMID 35684522, 2022). "Immunohistochemistry also confirmed EGFR expression in the same areas confirmed by pathologist to be tumor." (PMID 36357495, 2022). "In the present study, to verify that AZD3759 exerted anti-tumor properties not only by inhibiting EGFR signaling, but also by suppressing JAK1 signaling, we established JAK1-overexpressed PC-9 cells." (PMID 34738874, 2022). "The subsequent in vivo experiments also showed that TFAP2C knockdown led to a decrease in cisplatin-induced EGFR levels and further inhibited tumor growth." (PMID 36230734, 2022). "In the hereby presented proof-of-concept study, targeted phagocytosis for cancer immunotherapy was substituted by targeting MerTK on macrophages and the epidermal growth factor receptor (EGFR) that is overexpressed on a plethora of tumour types." (PMID 36555321, 2022). "The IFN-γ and EGFR have used Janus kinase 2 (JAK2) as standard signaling to transmit external or internal signals to tumor cells, respectively." (PMID 37305016, 2022). "Cetuximab works by blocking EGFR, thus inhibiting downstream EGFR signaling, negatively impacting tumor cell proliferation, invasion, and angiogenesis." (PMID 35912261, 2022). "UV‐light exposure induced killing of tumor cells labelled with α‐EGFR‐CMNB‐FL comparable to the level of killing of cells labeled with α‐EGFR‐FL." (PMID 35146940, 2022). "EC is a tumor type with a generally high expression of epidermal growth factor receptor (EGFR), and EGFR overexpression is closely related to tumor invasion, metastasis, and poor outcome of EC." (PMID 35912182, 2022). "In 2004, a tyrosine kinase inhibitor (TKI) targeting epidermal growth factor receptor (EGFR) was reported to induce a dramatic tumor response compared with conventional chemotherapy in patients with NSCLC." (PMID 36508072, 2022). "In previous research, we characterized novel roles of twist1a and xmrk (an activated epidermal growth factor receptor (EGFR) homolog) in tumorigenesis and metastasis and proposed a new animal model for screening anti-tumor metastasis drugs." (PMID 35052775, 2022). "Since the EGFR signalling promotes proliferation in tumor the EGFR receptors often represent a marker of resistance with poor prognosis." (PMID 35255831, 2022). "Here, we revealed that EGFR signaling mediates TCTP-induced resistance of tumor cells to CTL-mediated killing and decrease of T cell infiltration into the tumor by regulating MCL-1 and CXCL10." (PMID 35440620, 2022). "After initial treatment with EGFR-TKI icotinib, EGFR T790M mutation developed, and this therapy was followed by osimertinib with tumor shrinkage." (PMID 36153311, 2022). "A combination of nanobody-mediated NIR-PIT, which targets vascular endothelial growth factor receptor 2 (VEGFR2) on tumor endothelial cells, and EGFR on tumor cells, has also shown improved efficacy in a coculture model of endothelial and cancer cells." (PMID 36276636, 2022). "This study suggests that extremely high binding affinities of protein vehicles like DARPin E01 (KD = 0.5 nM) are disadvantageous for the ubiquitously expressed tumor marker EGFR in an appropriate xenograft model." (PMID 35269611, 2022). "Our study showed that TFAP2C knockdown affected the activation levels of EGFR and NF-κB and enhanced the anti-tumor effects of cisplatin in vivo and in vitro." (PMID 36230734, 2022). "To determine the clinical relevance of the key regulators ChAT and AChE in ACh metabolism, we performed immunohistochemical analysis on 20 paired tumor biopsies taken before and after EGFR-TKI therapy." (PMID 36048538, 2022).
tumor (continued). "In the meantime, it was also potential for the combination between YB1 expression or inhibition and hot topics of tumor therapy, such as anti-EGFR, anti-PD-1 or anti-PDL-1." (PMID 35260638, 2022). "Our study reports on the real-time utility and feasibility of incorporating the evaluation of ctDNA liquid RAS/RAF/EGFR and the status of other relevant resistance mutations in blood in patients with prior anti-EGFR exposure and tissue RAS/RAF-wild-type tumor." (PMID 35837097, 2022). "As expected, they found that mice bearing CCOC PDX overexpressing EGFR showed a significant decrease in tumor weight following erlotinib treatment, while the PDX model lacking the EGFR expression did not responded to the treatment." (PMID 35359749, 2022). "Intracellular PTP domains can catalyze the dephosphorylation of β-catenin and epidermal growth factor receptor (EGFR), and are implicated in the function of R-PTP-κ as a tumor suppressor gene." (PMID 36551956, 2022). "In the current study, we used propensity score matching to reduce the selection bias and found that the residual tumor resection after partial response to EGFR-TKI or primary tumor resection followed by EGFR-TKI had clinical benefits in both PFS and OS." (PMID 36581631, 2022). "Bevacizumab, a recombinant humanized VEGF antibody, inhibits tumor angiogenesis, whereas EGFR inhibitors, such as cetuximab and panitumumab, block tumor cell proliferation." (PMID 35206832, 2022). "Consistent with a previous report, 26 (76.5 %) tumor biopsies collected at disease progression after EGFR TKIs treatment showed high level ERK phosphorylation on immunohistochemistry." (PMID 34973117, 2022). "Collectively, these data correlated with the elevated expression of Th1 cytokines and reduced expression of Th2 cytokines in the lungs of EGFR‐targeted immRNA‐RBCEVs treated mice, indicating Th1‐associated and CTL‐mediated anti‐tumour immune responses." (PMID 35430766, 2022). "Amivantamab is capable of blocking ligand-induced phosphorylation of EGFR and cMet, thus blocking the activation of the signaling pathway, transmitting signals downstream, and inhibiting the proliferation of tumor cells expressing relevant molecules." (PMID 35418149, 2022). "EGFR and PDGFRα downregulation as well as Akt-mTOR inactivation was detected in TN-treated HeLa xenograft tumor tissues." (PMID 39282148, 2022). "Among the differentially affected proteins, phosphorylation of epidermal growth factor receptor (EGFR) was highly increased in tumor cells treated with IL-10." (PMID 36038549, 2022). "Melphalan and EGFR inhibitor gefitinib combination therapy resulted in better tumor shrinkage than melphalan alone." (PMID 35145058, 2022). "Primary EGFR-sdCAR-T:tumor cell co-cultures were then monitored for tumor cell (red fluorescence) and CAR-T cell (green fluorescence) growth over 7 days without media changes." (PMID 35935988, 2022). "In this case, neratinib was used not only to enhance the tumor targeting ability via conjugation with an EGFR -targeting group, but also to prevent the tumor metastasis during PDT, via chemotherapeutic action." (PMID 35213974, 2022). "In ER- cases (n = 224), HER2low status was significantly associated with increased regional nodal positivity, lower density of tumor infiltrating lymphocyte and a lower protein expression of Ki-67 and EGFR compared to HER2- cases." (PMID 35902644, 2022). "Further studies showed that the signal interaction between c-Met and EGFR mediated anti-tumor resistance." (PMID 35978812, 2022). "Angiotensin receptor-1 (ATR1) signalling appears to be the major component of RAAS involved in tumour growth (by inducing angiogenesis) and tumour proliferation (by promoting vascular or epidermal growth factor receptor expression)." (PMID 34318387, 2022). "When the EGFR is abnormally activated, the dimerization or over-expression of ligand-dependent receptors leads to the manifestation of tumours which are epithelial in origin." (PMID 36140214, 2022).
tumor (continued). "The epidermal growth factor receptor-tyrosine kinase inhibits (EGFR-TKI) targeted therapy is a milestone in tumor treatment with remarkable effects." (PMID 36386893, 2022). "Many studies have shown that the dysregulation of EGFR signaling pathways including AKT, ERK and STAT3 is associated with tumor proliferation and survival." (PMID 35572726, 2022). "The FDA-approved EGFR/HER2 inhibitor varlitinib inhibits tumor growth and is used in cancer treatment." (PMID 36341365, 2022). "Gefitinib, an EGFR inhibitor diminished the activation of these protein induced by IL-10, and inhibited tumor cells migration." (PMID 36038549, 2022). "The capability of ZEGFR:03115 to target EGFR-expressing cells in vivo was evaluated using an orthotopic U87-MGvIII tumour model." (PMID 35057796, 2022). "LOUPE browser analysis indicated that EGFR was scattered in TMZ-R tumor cells, determining that the number of cells above the cutoff of EGFR expression in TMZ-R was significantly less than in TMZ-S." (PMID 36316307, 2022). "Oncogenes such as rat sarcoma virus (RAS), myelocytomatosis (MYC), and epidermal growth factor receptor (EGFR) serve as key drivers of tumor initiation and growth." (PMID 35864539, 2022). "Over half of the patients in our study carried EGFR driver mutations, and they showed relatively lower CD8+ T cell infiltration than the RAS‐MAPK mutation patients in tumor parenchyma." (PMID 35150094, 2022). "A universal CAR-T cell that expresses an Fc-gamma receptor (FcγR)-CAR such as CD16A158F and CD32A131R CARs has been generated, using multiple therapeutic antibodies to redirect T cells to antigen-expressing tumor cells including EGFR-overexpressing TNBC." (PMID 35795050, 2022). "To date, several tumor cell biomarkers, including MDM2/4, epidermal growth factor receptor mutation, DNMT3A, and FGF3/4/19, have been shown to be associated with HPD." (PMID 36428951, 2022). "In detail, EGFR overexpression, observed in 68% of cases, was correlated with tumor aggressiveness (p = 0.049), while ALK low expression in 92% was associated with stage (p = 0.048)." (PMID 35406495, 2022). "CD82 can weaken the EGF/EGFR induction signal and inhibit tumor metastasis, but the mechanism is still unclear." (PMID 35538033, 2022). "We suspected the importance of IFNγ by performing a kinetic experiment during which fresh tumor slices were exposed for different times to EGFR CAR T cells." (PMID 36189315, 2022). "All cases of IBC-NST with medullary pattern had strong (immunoexpression in more than 50% of tumor cells) membranous expression of E-cadherin, EGFR, and PD-L1 in the cancer cells." (PMID 34636027, 2022). "The overall estimated HR for PFS was 2.00 (95% CI: 1.73–2.31, p < .001), which indicated that EGFR+ in both tumor tissue and plasma at baseline is the worse prognostic factor for NSCLC treated with EGFR TKIs." (PMID 34427045, 2022). "The EGFR mutation was significantly associated with pure or mixed GGO, lower SUVmax, and smaller tumor diameter." (PMID 36276079, 2022). "The pathological clearance of EGFR-positive tumor cells after treatment and detection of the CAR-EGFR gene in tumor-infiltrating T cells in all four patients were observed in tumor biopsies." (PMID 35935943, 2022). "ING5 suppresses proliferation, migration, invasion and tumor growth of various cancer cells via the suppression of EGFR/PI3K/Akt, IL-6/STAT3, Akt/NF-κB/NF-κB/MMP-9 or IL-6/CXCL12 pathway." (PMID 36425530, 2022). "For example, secondary KRAS and NRAS mutations in exons 3 and 4 were found to emerge in tumor biopsies and in circulating tumor DNA from patients who progressed to anti-EGFR MoAbs." (PMID 36556139, 2022). "In this latter study, a better sensitivity was observed for tumours expressing high levels of EGFR and the safety profile was considered as overall manageable using prophylactic measures." (PMID 36380366, 2022).